Y_RNA (Y RNA )
Gene: Miscellaneous RNA gene on chromosome 16 (74,463,888 to 74,463,988, reverse strand). Ensembl gene ENSG00000207525.
Homologues: Orthologues: chimpanzee Y_RNA (99% identical), macaque Y_RNA (91% identical), dog Y_RNA (80% identical), tropical clawed frog Y_RNA (70% identical). Paralogues in human: Y_RNA (87% identical), RNY3 (86% identical), Y_RNA (86% identical), Y_RNA (85% identical), Y_RNA (84% identical), RNY3P1 (83% identical), RNY3P14 (83% identical), Y_RNA (83% identical), Y_RNA (82% identical), RNY3P13 (81% identical), RNY3P16 (81% identical), RNY3P4 (81% identical), and 94 more.